LAMC3 (laminin subunit gamma 3)
Description:
Binding to cells via a high affinity receptor, laminin is thought to mediate the attachment, migration and organization of cells into tissues during embryonic development by interacting with other extracellular matrix components.
Synonyms: DKFZp434E202; OCCM
Tractability: Antibody: its Gene Ontology location is reachable by antibodies, with high confidence; UniProt places it where antibodies can reach, with medium confidence; UniProt predicts a signal peptide or a membrane-spanning region. PROTAC: ubiquitination databases record sites on it. Other modalities: an approved drug acts on it.
Gene: Protein-coding gene on chromosome 9 (131,009,149 to 131,094,473, forward strand). Ensembl gene ENSG00000050555.
Subcellular location: Secreted, extracellular space, extracellular matrix, basement membrane
Pathways (Reactome):
Extracellular matrix organization: Formation of the dystrophin-glycoprotein complex (DGC); Laminin interactions; Non-integrin membrane-ECM interactions
Developmental Biology: Developmental Lineage of Pancreatic Ductal Cells
Disease: Attachment of bacteria to epithelial cells
Signal Transduction: MET activates PTK2 signaling
Gene Ontology:
Molecular function: extracellular matrix structural constituent; structural molecule activity
Biological process: substrate adhesion-dependent cell spreading
Cellular component: basement membrane; extracellular matrix; extracellular region; laminin-12 complex; laminin-14 complex; laminin-15 complex; membrane
Genetic constraint (gnomAD): Loss-of-function variants: 124 observed, 158.34 expected, observed/expected ratio (o/e) 0.78, 90% interval 0.68 to 0.91. The upper end of that interval is the gene's LOEUF score, 0.91, which puts it in group 3 of 6, group 1 being the genes least tolerant of losing a copy. Missense variants: 1,979 observed, 2,077.7 expected, observed/expected ratio (o/e) 0.95, 90% interval 0.92 to 0.99. Synonymous variants: 867 observed, 872.06 expected, observed/expected ratio (o/e) 0.99, 90% interval 0.94 to 1.05.
Gene-disease validity (ClinGen):
ClinGen rates the evidence that LAMC3 causes each of these diseases.
complex neurodevelopmental disorder (autosomal dominant): Disputed. A disorder that involves more than one phenotype associated with the central nervous system, including but not limited to intellectual disability, autism, and seizures (epilepsy).
Homologues: Orthologues: chimpanzee LAMC3 (98% identical), macaque LAMC3 (95% identical), pig LAMC3 (84% identical), dog LAMC3 (82% identical), rat Lamc3 (75% identical), mouse Lamc3 (75% identical), guinea pig LAMC3 (72% identical). Paralogues in human: LAMC1 (43% identical), LAMA5 (28% identical), LAMA3 (24% identical), LAMA1 (24% identical), LAMB2 (24% identical), LAMA2 (23% identical), LAMB1 (23% identical), LAMB4 (23% identical), HSPG2 (23% identical), USH2A (19% identical), LAMC2 (19% identical), AGRN (14% identical), and 15 more.
Diseases named in the same sentence as LAMC3 in open-access papers:
LAMC3 is named in the same sentence as 39 diseases in open-access papers, as found by Europe PMC text mining. Sharing a sentence is not in itself a finding about the gene and the disease. The quoted sentences say what the papers report.
epilepsy (4 papers, 2019 to 2025). A brain disorder characterized by episodes of abnormally increased neuronal discharge resulting in transient episodes of sensory or motor neurological dysfunction, or psychic dysfunction. "Variants in EMC10 have been related to neurodevelopmental disorders and intellectual disability, and alterations in LAMC3 have been linked to cortical development anomalies and epilepsy." (PMID 41009814, 2025). "Structurally, the laminin subunit α5 forms heterotrimers with laminin subunits β1/β2 and γ1/γ3, which were encoded by LAMB1, LAMB2, LAMC1, and LAMC3 that were associated with neurodevelopmental diseases and epilepsy." (PMID 35663266, 2022). "The SCN1A gene encodes a subunit of sodium channel, previously associated with epilepsy and indicated as the candidate gene for ASDs while the LAMC3 gene is expressed in the cortex and limbic system." (PMID 30627967, 2019). "The administration of levetiracetam may be a relatively effective method to control epilepsy associated with LAMC3 variants." (PMID 34354730, 2021). "Four of them, in FOXP1, GRIN2B, SCN1A, and LAMC3 genes, were classified as potentially pathogenic and probably were associated with ASD, ID, and epilepsy." (PMID 30627967, 2019).
ovarian carcinoma (4 papers, 2022 to 2025). A malignant neoplasm originating from the surface ovarian epithelium. "LAMC3 is linked to drug resistance in ovarian cancer, while IL-7 exerts potent immunomodulatory effects and can act on tumor cells to exert anti-tumor activity." (PMID 41179658, 2025). "Low expression of LAMC3 is associated with malignant progression and poor prognosis of ovarian cancer (OC), which is expected to become a new therapeutic target and prognostic marker for clinical treatment." (PMID 38307919, 2024). "Low expression of LAMC3 may be associated with poor prognosis and malignant progression in OC of ovarian cancer." (PMID 36531485, 2022). "Studies have shown that interfering with LAMC3 expression can reduce the carboplatin resistance of ovarian cancer cells." (PMID 41179658, 2025). "LAMC3 is one of the most representative genes of a signature that has been validated to be used as an independent prognostic factor for breast cancer in individualized treatment, and its low expression has also been related to a worse prognosis in ovarian cancer." (PMID 40140215, 2025).
breast carcinoma (3 papers, 2022 to 2025). "Of these twenty, three showed evidence of association with LoF variants for overall breast cancer (ZFAND1, TYRO3, TMEM206/PACC1), and a further six with breast cancer subtypes (DNAH11, PARP2, LAMC3, MTMR11, EPN3, SLC22A10)." (PMID 35884425, 2022). "Furthermore, in non-muscle invasive bladder cancer, colorectal cancer, and breast cancers, high levels of laminin γ3 (LAMC3) expression have been linked to a positive prognosis." (PMID 37686118, 2023). "We found nominal evidence of association with breast cancer overall for LoF variants in three genes (ZFAND1, TMEM206/PACC1, and TYRO3), with ER-negative breast cancer in two genes, DNAH11 and PARP2, and with ER-positive disease in four genes LAMC3, MTMR11, EPN3, and SLC22A10." (PMID 35884425, 2022).
polymicrogyria (3 papers, 2019 to 2021). A developmental brain abnormality characterized by an excessive amount of small convolutions on the surface of the brain and cognitive dysfunction. "The clinical features of patients with OCCM caused by LAMC3 gene variants includes seizures, developmental delay or degeneration and pachygyria and polymicrogyria." (PMID 34354730, 2021). "Finally, pachygyria and polymicrogyria were the most representative imaging feature of patients with the LAMC3 gene variant." (PMID 34354730, 2021). "The genes FIG4 and LAMC3 were reported to be highly correlated with the polymicrogyria and cortical malformations, respectively." (PMID 31105557, 2019). "This work identified novel compound heterozygous variants in the LAMC3 gene that causes OCCM with recurrent seizures without polymicrogyria and pachygyria." (PMID 34354730, 2021).
endometriosis (2 papers, 2017 to 2022). The growth of functional endometrial tissue in anatomic sites outside the uterine body. "Of these eight loci, three were associated with all endometriosis (LAMC3, CAPN14 and DEFA1), and six with Stage B disease (NAALADL2, NR2C1, C14orf132, FOXP2, CDH20 and LAMC3)." (PMID 28333195, 2017).
glioma (2 papers, 2017 to 2024). A benign or malignant brain and spinal cord tumor that arises from glial cells (astrocytes, oligodendrocytes, ependymal cells). "A four-gene signature (ACTN1, AQP1, LAMC3, NRM) prognostic risk model was constructed among the differentially expressed genes (DEGs) identified in the grade II/III gliomas molecular subtypes." (PMID 38307919, 2024). "Our finding suggested that stimulating the Wnt/β-catenin signaling pathway could reduce the cell invasion of glioma cells by inhibiting the gene expression of Col1A1, LAMC3, and CD44." (PMID 28837560, 2017). "In this study, we constructed a novel and highly robust four-gene signature (ACTN1, AQP1, LAMC3, and NRM) based on EMT-related genes to predict grade II/III gliomas prognosis." (PMID 38307919, 2024).
small cell lung carcinoma (2 papers, 2020 to 2023). Small cell lung cancer (SCLC) is a highly aggressive malignant neoplasm, accounting for 10-15% of lung cancer cases, characterized byrapid growth, and early metastasis. "Downstream target proteins including LAMC1, LAMC3, CDK2 and FN1 were enriched in the cancer‐related pathways in small cell lung cancer." (PMID 35668574, 2023).
COVID-19 (1 paper, 2023). A disease caused by infection with severe acute respiratory syndrome coronavirus 2. "The most changed components of BM included laminins (LAMB2, LAMA2, LAMC3, LAMB1, LAMC1, and LAMA5) and proteoglycans (COL18A1, HSPG2, and AGRN), with some BM specific collagens (IV, VIII, XVIII, and V collagens) remaining in COVID-19 brains, as compared with the control brains." (PMID 36609561, 2023).
developmental delay (1 paper, 2017). "It was unclear whether the lack of thoracic duct in Lamc3 SBMO embryos is a result of developmental delay, caused by an earlier developmental defect or as a direct result of γ3-deficiency." (PMID 29417095, 2017).
dilated cardiomyopathy (1 paper, 2025). Cardiomyopathy which is characterized by dilation and contractile dysfunction of the left and right ventricles. "Lamc3, for instance, was involved in the PI3K-Akt signaling pathway, while Tpm3 and Itga10 were associated with dilated cardiomyopathy." (PMID 40606020, 2025).
Hydrocephalus (1 paper, 2019). Hydrocephalus is an active distension of the ventricular system of the brain resulting from inadequate passage of CSF from its point of production within the cerebral ventricles to its point of absorption into the systemic circulation. "On the basis of our quantitative rules, hydrocephalus-inducing protein has a relatively high expression level (>1.47) and laminin subunit gamma-3 precursor has a relatively low expression level (<0.42) at the proteomic level." (PMID 31850330, 2019). "Re-aligning to effective proteins hydrocephalus-inducing protein and laminin subunit gamma-3 precursor, such rule corresponds to recent publications and related databases." (PMID 31850330, 2019).
kidney cancer (1 paper, 2022). Primary or metastatic malignant neoplasm involving the kidney. "Of the three members of the LAMC family, LAMC1 and LAMC2 were upregulated in kidney cancers, while LAMC3 was downregulated in kidney cancers." (PMID 36188228, 2022).
liver steatosis (1 paper, 2024). "However, the other liver steatosis gene markers, such as Thbs2, Lum, Lamc3, Lama2, Akr1b10, Col4a4, A2m, and C7, were not significantly different between the db-HF and db-HC groups." (PMID 38613031, 2024).
Obesity (1 paper, 2025). Accumulation of substantial excess body fat. "From this analysis, methylation data (β values) of cancer-related genes previously identified in the DNA of leukocytes from patients with obesity after following a VLCKD to lose weight were isolated (CCND1, MAPK10, GLI2, LAMC3 and CTNNA2)." (PMID 40140215, 2025).
occipital cortical malformations (1 paper, 2022). "Variants in LAMC3 were the causes of occipital cortical malformations (OMIM #614115), and the affected individuals experienced seizures." (PMID 35663266, 2022).
oral cancers (1 paper, 2023). "We also confirmed the previously reported oral cancer susceptibility loci at the TERT-CLMPT1L locus on 5p15.33, thet 4q23 ADH1B locus, and the LAMC3 locus on 9q34.12 in Taiwanese populations." (PMID 36769103, 2023). "For other GWAS-identified oral cancer susceptibility loci in European populations, we were able to replicate the loci on 5p15.33, the 4q23 ADH1B locus, and the LAMC3 locus on 9q34.12." (PMID 36769103, 2023). "These GWAS identified at least nine genetic susceptibility regions for oral cancers, including 2p23.3 (GPN1), 4q21 (HEL308 and FAM175A), 4q23 (ADH1B, ADH1C, ADH7), 5p15.33 (CLPTM1L), 6p21 (HLA), 6p22.1 (ZNRD1-AS1), 9p21.3 (CDKN2A–CDKN2B), 9q34.12 (LAMC3), and 12q24 (ALDH2)." (PMID 36769103, 2023).
Seizure (1 paper, 2021). A seizure is an intermittent abnormality of nervous system physiology characterized by a transient occurrence of signs and/or symptoms due to abnormal excessive or synchronous neuronal activity in the brain. "Seizure was the most common clinical feature of patients with OCCM caused by LAMC3 gene variants." (PMID 34354730, 2021).
toxoplasmosis (1 paper, 2018). A parasitic disease contracted by the ingestion or fetal transmission of toxoplasma gondii. "The toxoplasmosis pathway encompasses JAK-STAT signalling as well as extra-cellular matrix interactions and laminins (LAMA2 and LAMC3)." (PMID 29447208, 2018).
cancer (11 papers, 2017 to 2025). A tumor composed of atypical neoplastic, often pleomorphic cells that invade other tissues. "VLCKD-induced nutritional ketosis promoted changes in the methylation of 18 genes (20 CpGs; 17 hypomethylated, 3 hypermethylated) belonged to cancer-related pathways with MAPK10, CCN1, CTNNA2, LAMC3 and GLI2 being the most representative genes." (PMID 40140215, 2025). "The roles of LAMC3 and KCTD1 are essential in the development and differentiation of the nervous system, while recent studies on its involvement in carcinoma have yet to be sufficient." (PMID 40584831, 2025).
tumor (10 papers, 2019 to 2025). "LAMA2, encoding a subunit of laminin protein, has been identified as a tumor suppressor in a recent genomic study and LAMC3 is another member of this gene family." (PMID 31722693, 2019). "The ECM-related genes, DCN, COL11A1, LAMC3, and COL25A1, were also significantly downregulated in PVTT, compared with primary tumor tissues, indicating that the ECM is involved in macrovascular invasion by HCC." (PMID 34504839, 2021). "However, LAMA1 was not statistically significantly different between groups, while LAMC3 and LAMB4 showed slight decreases in expression in tumour samples." (PMID 37779898, 2023). "While all three variants confirmed by SP-ddPCR (i.e., LAMC3 c.1241G>A, NRXN3 c.308G>A, and ASNA1 c.193C>T) were present in the surrounding colon mucosa, they were absent in the matched cancerous tissues, advocating a negative selection during tumor evolution." (PMID 37923774, 2023).
LAMC3 also shares sentences with these, for which no sentence is quoted: colorectal cancer (2 papers); fibrosis (2); Pachygyria (2); amoebiasis (1); Congenital muscular dystrophy type 1A (1); dystroglycanopathies (1); gastric cancer (1); infection (1); Intellectual disability (1); liver fibrosis (1); lung adenocarcinoma (1); lung carcinoma (1); Macrocephaly (1); major depressive disorder (1); melanoma (1); memory impairment (1); microcephaly (1); neurodevelopmental disorder (1); post-traumatic stress disorder (1).